SMAD3 (SMAD family member 3)
Diseases named in the same sentence as SMAD3 in open-access papers (continued):
Sharing a sentence is not in itself a finding about the gene and the disease.
aneurysm (continued). "Moreover, it would be interesting to investigate whether the observed differences in SMA and SM22 expression and ECM formation is specific for P/LP SMAD3 variants or whether these features are observed in other aneurysm genes as well." (PMID 38538566, 2024). "In addition, our conditional Ilk mutant mice might prove useful as a model to study aortic aneurysms caused by reduced Smad3 signaling, as occurs in the newly described aneurysms-osteoarthritis syndrome, for example." (PMID 23744273, 2013). "Other disruptions in the TGF-B signaling pathway, such as in Loeys-Dietz syndrome, as well as GLUT10 and SMAD3 mutations, also exacerbate vascular wall damage and favor the development of TAA aneurysms." (PMID 40176978, 2025). "In line with the clinical presentation of the patients in this study, several TAAD disease genes (e.g., SMAD3 and TGFBR1) are associated with a broad phenotypic spectrum including aneurysms/dissections of other arteries in addition to the aorta." (PMID 41056017, 2025). "Heterozygous P/LP variants in SMAD3 (OMIM 603109) cause Loeys-Dietz Syndrome type 3 (LDS3, OMIM 613795, ORPHA 284984), also known as aneurysms-osteoarthritis syndrome (AOS)." (PMID 38538566, 2024). "Within the TAV dilated individuals there was a trend towards decreased age and increased SMAD3 phosphorylation in those with root aneurysms compared to those with tubular aneurysms (P = 0.10 and 0.08, respectively)." (PMID 36104385, 2022). "Taken together, those independent studies using different lines of SMAD3 knockout mice demonstrated that SMAD3 is critical for protecting vessel walls from aneurysm formation." (PMID 35517795, 2022). "SMAD3 pathogenic variants can give rise to a form of H‐TAD, also characterized by osteoarthritis, hence the designation Aneurysm Osteoarthritis Syndrome." (PMID 29717556, 2018). "Although three studies using two Smad3 knockout mouse lines reveal the protective roles of SMAD3 via similar mechanisms, the functional roles of defective SMAD3 in human aneurysms appear to be more complex." (PMID 25985281, 2015). "To access SMAD3 expression patterns in the aneurysms, we performed IHC assays using abdominal aorta tissues from both AAA patients and age–matched controls." (PMID 25985281, 2015). "The activation of SMAD2 in the nucleus as indicated by the phosphorylated SMAD2 also significantly increased in the aneurysms of Smad3−/− mice using the antibody recognizing phosphorylated SMAD2/3." (PMID 25985281, 2015). "Taken together, these three independent studies using two different Smad3 knockout mouse lines demonstrate that SMAD3 is critical to protect the vessel wall from aneurysm formation." (PMID 25985281, 2015). "Unfortunately, it is not easy to have access to a number of small AAAs to validate the protective roles of SMAD3 in human aneurysms." (PMID 25985281, 2015). "Since inflammation is prominent in the aneurysms, we examined the expression of p65 (aka RELA), the master regulator of cellular proinflammatory responses in the vessel wall of the aneurysms in Smad3−/− mice." (PMID 25985281, 2015). "Mutations in mothers against decapentaplegic homolog 3 (SMAD3), one of the intracellular mediators of TGF-β signalling, are known to cause the aneurysm-osteoarthritis syndrome, presenting with early-onset polyarticular OA." (PMID 26395178, 2015). "Lipopolysaccharide‐triggered inflammation confirmed that enhanced aortic macrophage recruitment was essential for aneurysm formation in angiotensin II–infused SMAD3‐knockout mice." (PMID 23782924, 2013). "TGFß signaling through SMAD2/SMAD3 contributes to aortic remodeling in TAV, whereas TGFß-independent activation of SMAD3 may underlie aneurysm formation in BAV/UAV aortas." (PMID 36104385, 2022). "In addition, SMAD3 cis-acting eQTL operating in primary osteoarthritis and in the aneurysms and osteoarthritis syndrome was reported." (PMID 33593158, 2021).
aneurysm (continued). "The opposite effects of SMC-specific Notch1 haploinsufficiency on Smad2 and Smad3 indicate that the crosstalk between Notch1 and Tgf-β signaling pathway in aneurysm may have differential effects on the downstream targets." (PMID 28562688, 2017). "Since the SMAD3∆C lacks the TGFBR interaction domain and phosphorylation site for the SMAD3 activation, it is not surprising that loss of SMAD3 and the expression of the inactive SMAD3∆C protein induce aneurysm formation via similar mechanisms." (PMID 25985281, 2015). "Mutations in the SMAD3 gene, which encodes a protein critical for cellular signaling downstream of the TGF-β receptors after ligand binding, are responsible for LDS type 3 (LDS3, MIM#613795), also known as Aneurysms–Osteoarthritis Syndrome." (PMID 25163805, 2014). "Apart from SMAD3, the relationship between SMAD4 and aneurysms also has been studied." (PMID 34093163, 2021). "Indeed the underlying molecular mechanisms of the intricate interplay of TGF-β, SMAD2, SMAD3 and SMAD4 in the pathogenesis of aneurysm remains to be determined." (PMID 25985281, 2015). "Based upon published results and our own, we propose that β1 integrin, ILK, Pinch1, Rac1 and Smad3 participate in a common pathway involved in an NCC morphogenetic program during cardiovascular development that, when perturbed, results in aneurysms in the ascending aorta." (PMID 23744273, 2013).
prostate carcinoma (37 papers, 2014 to 2025). A carcinoma that arises from epithelial cells of the prostate gland. "Research indicates that the dysregulation of the E2F5/p38/SMAD3 axis is associated with uncontrolled cell proliferation in prostate cancer (PCa)." (PMID 39085482, 2024). "Further analysis showed that Smad3 overexpression in prostate cancer cells could overcome the decreased HIF-1α and PFKP caused by docetaxel." (PMID 36536346, 2022). "ONECUT2 activates SMAD3 and EPAS1 which mediate survival of tumor cells under hypoxic conditions as shown recently for SMAD3 in prostate cancer and in this study for EPAS1 in BPDCN." (PMID 38474011, 2024). "We next turned to the canonical readout of TGFβ signaling hosphor-SMAD3 (pSMAD3) and were surprised to see enriched IHC staining in blastic features of metastatic prostate cancer in bone." (PMID 34956082, 2021). "The NR2C2 also increased prostate cancer invasion by altering TGFβR2/p-Smad3 signalling by decreasing miR-373-3p expression and further, promotes prostate cancer metastasis through upregulation of CCL2/CCR2 signalling." (PMID 33113804, 2020). "The IPA demonstrated that important biochemical molecules such as VEGF, ERK1/2, p38 MAPK and PLA2G7, NADPH oxidase, SMAD3 and ODC1 were involved in the biological network associated with berberine against prostate cancer." (PMID 29029409, 2017). "Taken together, these data indicate that Notch growth suppressing effects in prostate cancer cells with low Notch1 levels are mediated by p21WAF1/CIP1 in a Smad3 dependent manner." (PMID 27384993, 2016). "Another positive regulator of p21WAF1/CIP1 expression is Smad3, which was also previously reported to be downmodulated in prostate cancer." (PMID 27384993, 2016). "Transcriptome profile showed that RUNX2 was associated with the malignant behavior of prostate cancer, including invasion and bone spread by up-regulating MMP9, SNAI2 and Smad3." (PMID 27007162, 2016). "In37, SMAD3 is experimentally demonstrated to repress the androgen receptor (AR) through MH2 domain to regulate the androgen-signaling pathway in prostate cancer cells." (PMID 26648121, 2015). "SMAD3 is a key mediator of TGF-β signaling pathway regulating tumor growth and metastasis, and overexpression of SMAD3 was also detected in prostate cancer." (PMID 25408144, 2014). "SMAD3 reportedly supports the growth of prostate cancer cells under hypoxic conditions, further supporting the notion that hypoxic adaptation may represent an important oncogenic function of ONECUT2 and its target genes SMAD3 and EPAS1 in BPDCN." (PMID 38474011, 2024). "Taken together, these data provide in vivo evidence that docetaxel could inhibit prostate cancer progression through Smad3-mediated glycolysis." (PMID 36536346, 2022). "The prostate cancer progression was activated when the SMAD3 was upregulated." (PMID 35291909, 2022). "In addition, Smad3 linker phosphorylation reportedly enhanced cell motility via a Pin1-dependent mechanism in PC-3 human prostate cancer cells and normal murine mammary gland epithelial cells." (PMID 36549646, 2022). "This study suggests that SMAD3 could be targeted to inhibit AR in prostate cancer." (PMID 36727462, 2023). "Moreover, ectopic expression of Smad3 in prostate cancer cells could overcome the decreased HIF-1α expression and its target gene PFKP caused by docetaxel treatment." (PMID 36536346, 2022). "In prostate cancer, ONECUT2 operates as an oncogene by activating expression of SMAD3 which regulates tumor growth under hypoxic conditions." (PMID 38474011, 2024). "The SMAD3 peak in AR intron 3 overlapped with H3K27ac ChIP-seq and ATAC-seq peaks in datasets of prostate cancer." (PMID 36727462, 2023). "AR and SMAD3 mRNAs were upregulated in datasets of metastatic prostate cancer and CRPC compared with primary prostate cancer." (PMID 36727462, 2023).
prostate carcinoma (continued). "In prostate cancer cells, overexpression of Smad2/3 enhances aerobic glycolysis independently of TGF-β stimulation but requires PKCε-mediated phosphorylation of the Smad3 linker region, which assists binding of Smad3 to the promoter of glycolytic genes." (PMID 35359452, 2022). "In prostate cancer cells, TGF-β induces AR activation of its target genes, while AR also represses TGF-β signaling through interaction with Smad3." (PMID 29249975, 2017). "A SMAD3 PROTAC inhibitor reduced levels of AR, AR-V7 and AR targets in prostate cancer cells." (PMID 36727462, 2023). "Moreover, the recruitment of RbBP5 component of COMPASS-like complexes and the formation of H3K4me3 at SNAIL transcription start site during epithelial-mesenchymal transition are dependent on SMAD3 and CBP in the DU145 prostate cancer cell line." (PMID 34202528, 2021). "miR-15a/16 target and downregulate expressions of SMAD3 and ACVR2A, resulting in attenuated expression of TGF-β dependent genes, including MMP2, E-cadherin, Snail, and Twist, and leading to inhibition of EMT and invasion of prostate cancer cells." (PMID 31842336, 2019). "Similarly, decreased expression of miR-505-3p contributes to prostate cancer progression by targeting SMAD2 and SMAD3, and stimulating migration and invasion." (PMID 31842336, 2019). "Berberine could effectively regulate SMAD3 and then affected the TGF-β signaling pathway, and then to treated prostate cancer." (PMID 29029409, 2017). "However, depletion of CDC7 in our advanced prostate cancer cell line led to a decrease in TGF-β1, SMAD3, and MMP9 expressions and therefore targeting CDC7 could also be a method to inhibit TGF-β driven metastasis caused by ADT." (PMID 41413594, 2025). "Besides the direct regulation by HIF-1α and SMAD3, through some other public ChIP-Sequencing dataset, we also found that, in PCa, CDCA2 was a directly regulated by MEN1, which function as an oncogene in prostate cancer (GEO: GSE132827)." (PMID 32509575, 2020). "In another study using the prostate cancer cell line DU145, pretreatment with the BRD3 degrader MZ1 did not affect Smad3 phosphorylation induced by TGF-β." (PMID 40869394, 2025).
bladder cancer (35 papers, 2012 to 2025). "Upon genome-wide expression profile screening, high expression of SMAD3 was found to be significantly associated with worse overall survival and higher tumor invasive depth in bladder cancer." (PMID 35205713, 2022). "Similarly, in bladder cancer cells exhibiting nutrient deficiency, EMT induces autophagy through the TGF-β1/Smad3 signaling pathway and promotes the invasion of bladder cancer cells." (PMID 37666811, 2023). "This study is the first to reveal the mechanism by which the Smad3/CISD2 signaling axis regulates ferroptosis in mesenchymal-like bladder cancer cells." (PMID 41413023, 2025). "RNA-seq revealed significant downregulation of Smad3 in ferroptosis inducer treated mesenchymal-like bladder cancer cells." (PMID 41413023, 2025). "It has been demonstrated that has-miR-665 inhibits the migration of bladder cancer cells by regulating the expression of SMAD3 and SNAIL." (PMID 38678587, 2024). "miR-665 inhibits epithelial-mesenchymal transition and suppresses progression by blocking the SMAD3/SNAIL axis in bladder cancer." (PMID 38097567, 2023). "To date, this is the first connection identified between the LINC02470–miR-143-3p–SMAD3 axis and bladder cancer progression." (PMID 35205713, 2022). "This study indicated that LINC02470 promotes bladder cancer cell viability, migration, invasion, and in vivo tumorigenicity by sponging miR-143-3p and consequently rescuing SMAD3 translation to activate the TGF-β-induced EMT process." (PMID 35205713, 2022). "In conclusion, this is the first study to demonstrate that LINC02470 plays a pivotally regulatory role in the promotion of TGF-β-induced EMT through the miR-143-3p/SMAD3 axis, thereby aggravating bladder cancer progression." (PMID 35205713, 2022). "In conclusion, this is the first study to demonstrate that LINC02470 plays a significant regulatory role in EMT promotion through the miR-143-3p–SMAD3 signaling pathway, thereby aggravating bladder cancer progression." (PMID 35205713, 2022). "SMAD3 is downregulated by miR-136 in bladder cancer which is driven by the hypomethylation of PlncRNA-1 promoter." (PMID 34168984, 2021). "A previous study demonstrated that miR-1305 inhibited bladder cancer progression by the TGF-β2/SMAD3 pathway." (PMID 34635639, 2021). "Among them, SMAD3 mediates epithelial-mesenchymal transition which affects the invasion and migration of Bladder Cancer." (PMID 31001321, 2019). "Additionally, indirect suppression of upstream TGF-β signaling also verified that SMAD3 is necessary to promote EMT in bladder cancer cells." (PMID 35205713, 2022). "The findings of the present study indicate that miR-143-3p directly targets and suppresses SMAD3 expression to inhibit the EMT process in bladder cancer cells; however, high LINC02470 expression sponges miR-143-3p to rescue SMAD3 translation and recovers the EMT process." (PMID 35205713, 2022). "First, the LINC02470–miR-143-3p–SMAD3 ceRNA axis participates in bladder cancer progression." (PMID 35205713, 2022). "SMAD3 could activate the TGF-β-induced EMT process of bladder cancer cells." (PMID 35291909, 2022). "For instance, in a mouse model of bladder cancer, TGFβ has been recently shown to correlate with high VISTA expression, while the TGF-β-Smad-3 signalling pathway has previously been shown to positively regulate VISTA expression in human T lymphocytes." (PMID 40316725, 2025). "It was confirmed that miR-5195-3p inhibited the proliferation and invasion of bladder cancer cells by targeting the oncogene KLF5.21 and inhibited the activity of HCT116 cells by inhibiting the expression of TGFβR1, TGFβR2, SMAD3 and SMAD4." (PMID 37328795, 2023). "Our findings demonstrate that the LINC02470–miR-143-3p–SMAD3 ceRNA axis directly regulates the major transcription factor of TGF-β signaling, SMAD3, thereby inducing the EMT process in bladder cancer and enhancing the aggressiveness of bladder cancer cells." (PMID 35205713, 2022).
bladder cancer (continued). "Functional rescue experiments showed that CISD2 overexpression in Smad3-knockdown mesenchymal-like bladder cancer cells reversed abnormal increases in Fe2+, ROS, LPO, and MDA while restoring GSH levels, indicating that Smad3 modulates ferroptosis through a CISD2-dependent pathway." (PMID 41413023, 2025). "Similarly, downregulation of miR-145 corresponded to higher SMAD3 expression and EMT process induction in nasopharyngeal cancer cells or inhibited TGFβR2 and SMAD3 in bladder cancer." (PMID 35205713, 2022). "In particular, it has been documented that GULP1 activates SMAD3 or inactivates AKT/PDK1 and MAPK in ovarian cancer cells, while it inhibits the nuclear translocation of NRF2 and subsequently reduces the expression of HMOX1 in bladder cancer cells." (PMID 34576193, 2021). "It is well known that TGF-β/Activin/Nodal signaling is transduced by SMAD2 and SMAD3, and increased TGF-β1 level can revert a malignant phenotype to a less aggressive phenotype in rat bladder carcinoma cell line lacking TGF-β1." (PMID 23251617, 2012).